ERCC1 (ERCC excision repair 1, endonuclease non-catalytic subunit)
Diseases named in the same sentence as ERCC1 in open-access papers (continued):
Sharing a sentence is not in itself a finding about the gene and the disease.
lung cancer (continued). "We found both protein and mRNA expression level of ERCC1 in EGFR exon 19 deletion lung cancer cell line (PC9) were lower than EGFR wild‐type cancer cell lines and noncancerous human bronchial epithelial cell lines." (PMID 31875360, 2020). "The purpose of this study was to assess the predictive role of particular single nucleotide polymorphisms in the promoter regions of topoisomerase 2‐alpha and ERCC1 genes in non‐small cell lung cancer patients." (PMID 31797573, 2020). "For example, ERCC1 is the most promising marker of resistance to cisplatin-based adjuvant therapy and the down-regulation of ERCC1-XPF by siRNA sensitizes lung cancer cells to cisplatin." (PMID 31615563, 2019). "Others found similar difficulties when studying ERCC1 expression using an 8F1 antibody in a large sample set from 2 phase 3 trials of adjuvant cisplatin in lung cancer." (PMID 30885775, 2019). "The aim of this study was to investigate polymorphism in the mentioned areas, converting nucleotide C to A at position 8092 (rs3212986) and exchanging nucleotide C with T at codon 118 (rs11615) in the ERCC1 gene in patients with lung cancer." (PMID 31245210, 2019). "High/positive ERCC1 expression was correlated with worse survival time in head and neck carcinomas, lung cancer, urothelial cancer, and colorectal cancer." (PMID 30417012, 2018). "The analysis of age stratification showed that ERCC1 rs735482 AC genotype had a protective role on lung cancer (OR = 0.560, 95%CI: 0.336‐0.934)." (PMID 30453383, 2018). "The aim of this study was to evaluate the possible relationship between several common genetic polymorphisms in DNA repair genes (ERCC1, ERCC2 and XRCC1) and the risk of developing RP in lung cancer patients receiving intensity modulation radiated therapy." (PMID 29416669, 2018). "Despite the controversy, researchers focused on understanding roles of ERCC1 in sensitizing the cisplatin-based chemotherapy for lung cancer." (PMID 30563166, 2018). "Although ERCC1 has a role as a prognostic marker in non–small-cell lung cancer (NSCLC), for patients with CRC, the definite prognostic value of ERCC1 expression has not been established yet." (PMID 28767665, 2017). "We previously showed that inhibition of ERCC1 expression in lung cancer cells increased drug-DNA adduct formation and reduced repair of carboplatin-DNA monoadducts and partially reversed chemoresistance." (PMID 26799320, 2016). "Depletion of endogenous ERCC1 expression significantly enhanced lung cancer cell death after treatment with cisplatin." (PMID 25505920, 2014). "The majority of studies on ERCC1 and cisplatin, in NonSmall Cell Lung Cancer (NSCLC) as well as in other solid tumours, share in common the finding that low-ERCC1 expression is associated with a better response to platinum-based chemotherapy." (PMID 24058603, 2013). "In this study, we also discovered that the PCYT1A gene expression level is significantly higher than the ERCC1 gene expression level in a certain population of lung cancer patient tissue samples." (PMID 23171216, 2012). "There is observation of platinum resistance in lung cancer A549 cells lines with high expression of ERCC1, and increased clinical evidence that overexpression of ERCC1 in NSCLC inhibits platinum efficacy." (PMID 22439756, 2012). "We performed a systematic review and, where possible, meta-analysis of study outcomes to produce evidence-based results on the prognostic and predictive utility of ERCC1 status in lung cancer, and identify further research needs." (PMID 22022380, 2011). "Previous studies have suggested that somatic ERCC1 expression level is both prognostic in lung cancer, and predictive of outcome to platinum-based chemotherapy." (PMID 22022380, 2011).
lung cancer (continued). "The IALT Biology Study used immunohistochemical analysis to determine the expression of the ERCC1 protein in the operative lung cancer specimens." (PMID 20461087, 2010). "The small interfering RNA (siRNA) targeting ERCC1 gene was designed and synthesized, and transfected to lung cancer cell A549/DDP." (PMID 20840811, 2010). "The aim of this study is to investigate the changes of cisplatin sensitivity by silencing ERCC1 gene in lung cancer cell." (PMID 20840811, 2010). "The Genotypic International Lung Trial (GILT) by the Spanish Lung Cancer Group conducted the first study to use ERCC1 mRNA status to customise chemotherapy in patients with previously treated NSCL cancer." (PMID 22275966, 2008). "In addition, excision repair cross-complementing group 1 (ERCC1) is largely reportable as a key player in this pathway and has been studied extensively in many diseases, including nonsmall-cell lung cancer." (PMID 37298600, 2023). "As few studies have explored the genetic factors affecting the quality of life, we first proposed the correlation between ERCC1, ERCC2 gene polymorphisms, and the quality of life of lung cancer patients, which provides a new perspective for the study of LC patients’ quality of life." (PMID 34284736, 2021). "In addition, the International Adjuvant Lung Cancer Trial (IALT) showed that those with ERCC1-positive tumors survived longer than those with ERCC1-negative tumors among patients who did not receive platinum-based chemotherapy." (PMID 34350111, 2021). "Furthermore, knockdown of either ERCC1 or XPF with siRNA in lung cancer cells resulted in defective repair of both intrastrand and interstrand cisplatin crosslinks, which is accompanied with increased cellular cytotoxicity." (PMID 33291532, 2020). "For preliminary experiments, A549 lung cancer cells were transfected with micelleplexes and Lipofectamine (LF) that contained 50 pmol of ERCC1-XPF siRNA, and protein knockdown was determined after 72 h via Western blot analysis with β-actin as a loading control." (PMID 32344513, 2020). "The conclusions were that the ERCC1 expression might be an independent prognostic factor for survival in lung cancer." (PMID 32397531, 2020). "In line with critical roles for ERCC1/XPF in ICL repair, we have previously shown that siRNA knockdown of ERCC1/XPF could enhance sensitivity of lung cancer cells to cisplatin." (PMID 30400270, 2018). "Moreover, the analysis after age stratification (Age < 60) indicated that AC genotype of ERCC1 rs735482 had a protective role for lung cancer (OR = 0.560, 95%CI: 0.336‐0.934)." (PMID 30453383, 2018). "In lung cancer, high ERCC1 expression is correlated to platinum chemotherapy resistance." (PMID 29160417, 2017). "In addition, cisplatin-induced ERCC1 expressions decreased by blocking ERK activation in lung cancer cell lines." (PMID 29156754, 2017). "Cancer cells overexpressing ERCC1 were correlated with drug resistance to chemotherapy containing cisplatin, carboplatin, or oxaliplatin in several types of tumors such as gastric, bladder, ovarian, colorectal, and lung carcinomas." (PMID 28388903, 2017). "Stratified analysis with 9 studies of 4,652 cases and 5,164 controls demonstrated that ERCC1 rs11615, but not rs3212986 polymorphism significantly increased lung cancer risk." (PMID 24841208, 2014). "Overall, this meta-analysis suggests that ERCC1 rs3212948 G>C, but not others, is a lung cancer risk-associated polymorphism." (PMID 24841208, 2014).
lung cancer (continued). "A polymorphism of ERCC1 C118T was associated with a higher risk of developing cancer and negative clinical outcomes in lung cancer." (PMID 25250341, 2014). "8F1 is one of the most commonly used monoclonal antibodies for evaluating ERCC1 expression levels in lung cancer patient tissues, but it has been noted that this antibody cross-reacts with an unknown protein." (PMID 23171216, 2012). "To facilitate our understanding of how much 8F1 nuclear immunostaining signal might be coming from 8F1-PCYT1A interaction, we wanted to compare the endogenous protein expression levels for PCYT1A and ERCC1 in lung cancer patients." (PMID 23171216, 2012). "However, four lung cancer patient samples exhibited higher PCYT1A mRNA expression levels than ERCC1 mRNA expression." (PMID 23171216, 2012). "In addition, prospective randomized trials of therapy based on expression levels of ERCC1, such as that performed in lung cancer, are needed." (PMID 22110495, 2012). "ERCC-1 and CEA might be associated with lung cancer development and its metastasis through different mechanism." (PMID 22890830, 2012). "RRM1 and ERCC1 overexpression has been extensively investigated as potential predictive markers of tumor sensitivity to conventional chemotherapy agents, most thoroughly in lung cancer." (PMID 22436573, 2012). "Reports concerning ERCC1 in resected lung cancer suggest that ERCC1 overexpression may improve treatment outcome by reducing DNA mutations during cancer progression." (PMID 19259093, 2009). "In studies of Caucasians, the haplotype encompassing the three SNPs: ERCC1 Asn118Asn, ASE-1 G-21A and RAI IVS1 A4364G was strongly associated to risk of post-menopausal breast cancer and lung cancer among women less than 55 years of age when diagnosed with their first cancer." (PMID 18289367, 2008). "Interestingly, two meta-analyses reported that SNPs in both ERCC1 and ERCC2 genes may play a significant role in lung cancer risk." (PMID 39735668, 2025). "Considering the evidence that ERCC1 could be a potential therapeutic target for enhancing responses to platinum-based chemotherapy in lung cancer, the development of small molecule inhibitors of XPF nuclease activity has been the focus of several studies from multiple research groups." (PMID 32344513, 2020). "Data from the presented study further indicated that rs3212986 polymorphism in 3ʹUTR of ERCC1 overlapped with CD3EAP may affect the repair of the damage induced by BPDE mainly via regulating ERCC1 expression and become a potential biomarker to predict smoking‐related lung cancer." (PMID 30453383, 2018). "Therefore, ERCC1 is considered to be one of the significant therapeutic target for lung cancer treatment, as targeting ERCC1 may possibly restore the therapeutic sensitivity to platinum-based chemicals." (PMID 30563166, 2018). "Our findings suggest that rs3212986 polymorphism in 3ʹUTR of ERCC1 overlapped with CD3EAP may affect the repair of the damage induced by BPDE mainly via regulating ERCC1 expression and become a potential biomarker to predict smoking‐related lung cancer." (PMID 30453383, 2018). "Many pathways may be responsible for the change of ERCC1 in cancer cells, including lung cancers." (PMID 30563166, 2018). "Researchers document changes of ERCC1 that contribute to this exceptional DNA repair signaling in cisplatin-resistant cancer cells that may actually make it possible to develop novel therapies for cisplatin-resistant lung cancer cancers." (PMID 30563166, 2018). "Furthermore, we found that the A allele (AA and CA + AA genotypes) of ERCC1 rs3212986 also exhibited an enhanced risk to develop lung cancer in smokers only (P < 0.05), but not in never smokers." (PMID 30453383, 2018).
lung cancer (continued). "In addition, the pilot in vivo xenograft data using H460 lung cancer cells provide the proof of principle that targeting ERCC1-XPF can enhance cisplatin potency and also highlights NSC16168 as a potential lead structure for future drug development efforts towards targeting ERCC1-XPF." (PMID 27650543, 2016). "Risk estimates suggested that ERCC1 rs2298881 is not a risk-associated polymorphism in lung cancer." (PMID 24841208, 2014). "Moreover, initial analyses suggested that ERCC1 rs11615 exerts a more profound effect on the susceptibility of non-smokers to lung cancer than that of smokers." (PMID 24841208, 2014). "Particularly, ERCC1 gene polymorphism may play roles to different extents in smoked-related and non-smoked-related lung cancer; however, very few of the studies in this meta-analysis separately reported SNP genotype counts for smokers and non-smokers." (PMID 24841208, 2014). "In these studies, the combination of cisplatin and curcumin or emodin produced significantly lower ERCC1 mRNA levels when compared with cisplatin alone, indicating that these products can downregulate both protein and mRNA expression of ERCC1 in these human lung cancer cell lines." (PMID 25505920, 2014). "Developing different doses for patients with or without the ERCC1 T allele might prevent nephrotoxicity in lung cancer patients." (PMID 25250341, 2014). "In 2006, a landmark article on personalized chemotherapy for lung cancer was published in the New England Journal of Medicine, which indicated that only patients with low expression of excision repair cross complementation 1 (ERCC1) benefit from adjuvant chemotherapy." (PMID 23737908, 2013). "This clearly demonstrates that in a certain lung cancer patient population, a significant amount of 8F1 immunoreactive signal could come from the 8F1-PCYT1A interaction and argues against the use of the 8F1 clone for ERCC1 IHC diagnostic assays." (PMID 23171216, 2012). "Recent studies of Asian and Western patients have firmly established that lipoprotein receptor-related protein-1, ribonucleotide reductase M1 (RRM-1), EGFR, and excision repair cross-complementing gene 1 (ERCC-1) may be useful molecular markers to guide drug selection in patients with lung cancer." (PMID 22890830, 2012). "Proteins that play a crucial role in this pathway, including excision repair cross-complementing group 1 (ERCC1), ERCC2, and ERCC5 have been widely studied in different types of tumors, including lung cancer." (PMID 39735668, 2025). "Our findings provide experimental evidence to support the use of ERCC1 and ERCC5 SNPs as potential biomarkers of specific types of lung cancer." (PMID 35069899, 2022). "To confirm that compound 6 was able to disrupt the interaction between subunits in the ERCC1-XPF heterodimer in cells, we performed PLA using A549 lung cancer cells exposed to 2 μM compound 6 or DMSO vehicle for 24 h." (PMID 35372043, 2022). "SNPs of ERCC1 and ERCC2 genes may affect the protein expression level and activity and affect the resection and repairability of the NER system, which are related to lung cancer susceptibility, chemotherapy effect and toxicity of platinum drugs, and prognosis of lung cancer." (PMID 34284736, 2021). "Therefore, ERCC1 and ERCC2 SNPs may be associated with the QoL of lung cancer patients." (PMID 34284736, 2021). "Emodin-induced cytotoxicity has been demonstrated in the lung cancer cell lines H1650, A549, H520, and H1703 through inactivation of ERK1/2 and down-regulation of ERCC1, and Rad51." (PMID 34073059, 2021).
lung cancer (continued). "The genes tested were TBP as a housekeeping gene, EGFR, ERCC1 and RRM1 as genes with potential predictive roles for lung cancer therapy, and HIF1 as a gene regulated by hypoxia, at least partially on RNA level." (PMID 30947297, 2019). "Not only did these compounds inhibit ERCC1/XPF activity in vitro, but this inhibition enhanced sensitivity to cisplatin in lung cancer cell lines." (PMID 30400270, 2018). "We previously have shown that ERCC1/XPF knockdown can sensitize ovarian and lung cancer cell lines to cisplatin." (PMID 30400270, 2018). "To date, ERCC1 was the most studied of the ERCC gene family in different cancers including GC, colorectal cancer, lung cancer, and ovarian carcinoma." (PMID 30417012, 2018). "Inhibitors of the ERCC1/XPA interaction with activity against colorectal and lung cancer cell lines have been reported and an in silico drug screen identified compounds that can disrupt ERCC1-XPF complex stability in cell lysates." (PMID 28903417, 2017). "According to our genome-wide transcriptomic analysis and Q-PCR validation, we found that the DNA damage-related genes ERCC1, XPC, and CRY1 were up-regulated in hinokitiol-treated lung cancer cells." (PMID 25105411, 2014). "In clinical studies, the expression of ERCC1 influenced the prognosis of the patients treated with cisplatin-based chemotherapy and chemoradiotherapy (CRT) in various cancers such as lung cancer." (PMID 22110495, 2012). "First, we compared the expression of six molecular biomarkers (MDR-1, LRP, RRM-1, EGFR, ERCC-1, and BRCA-1) in the primary lung carcinoma and the metastatic lymph nodes of patients with the two subtypes of NSCLC." (PMID 22890830, 2012). "The critical role of ERCC1 in carcinogen and platinum adduct removal by NER has led to a number of studies reporting the relationship between ERCC1 status and survival in lung cancer patients, predominantly in NSCLC." (PMID 22022380, 2011). "The aim of this study is to investigate the relationship between expression levels of ERCC1 and GST-pi, and clinicopathologic parameters and survival in patients with lung cancer." (PMID 20673515, 2010). "The expression levels of ERCC1 and GST-pi were detected by immunohistochemical staining on tissue micro-array sections made of 148 cases of lung cancer and 7 cases of normal lung samples." (PMID 20673515, 2010). "Moreover, E-X PPI2, E-X AS7, and panobinostat (a HDAC inhibitor) have been reported to silence ERCC1 and ACTL6A expressions in melanoma and ovarian/lung cancers, respectively, via in vitro and preclinical experiments." (PMID 40510426, 2025). "Indeed, small-molecule inhibitors that block the interaction between ERCC1 and XPF—two key factors in the nucleotide excision repair (NER) pathway—can enhance the cytotoxic effects of cisplatin and mitomycin C in lung cancer and colorectal carcinoma cells." (PMID 39582530, 2024). "ERCC1 and XRCC1 polymorphisms have also been significantly associated with the risk of lung cancer, especially in non-smokers 2-5." (PMID 35069899, 2022). "For example, a survey in lung cancer patients showed no clear correlation between ERCC1 mRNA levels and patient survival after cisplatin therapy." (PMID 33291532, 2020). "In lung cancer cell lines, PC9 cells showed increased ERCC1 expression after gefitinib treatment." (PMID 31875360, 2020). "The International Adjuvant Lung Cancer Trial (IALT) analysis showed that patients with ERCC1 protein negative tumors have better adjuvant cisplatin‐based chemotherapy results compared to patients with ERCC1 protein positive tumors." (PMID 31797573, 2020). "In this study, seven candidate SNPs in 3′UTR of DRC‐related genes including ERCC1 (rs3212986, rs2336219, and rs735482), OGG1 (rs1052133), MLH3 (rs108621), CD3EAP (rs1007616), and PPP1R13L (rs6966) were analyzed in 300 lung cancer patients and controls from the northeast of China." (PMID 30453383, 2018).